STAT3 (signal transducer and activator of transcription 3)
Diseases named in the same sentence as STAT3 in open-access papers (continued):
Sharing a sentence is not in itself a finding about the gene and the disease.
cancer (continued). "The deactivation of ERK and STAT3 can have significant consequences in cancer progression." (PMID 38612893, 2024). "Therefore, it is possible that the decline of epidermal EGFR-mediated STAT3 signaling switches the balance in favor of STAT1 activation as it is described for STAT3 knockout conditions in various model systems including cancer cells." (PMID 39521937, 2024). "Thus, p27pTpT interacts with STAT3, driving transcriptional programs governing stem cell expansion or maintenance in normal and cancer tissues." (PMID 38886396, 2024). "It remains unclear whether pharmacological inhibition of STAT3 activity, in combination with standard-of-care chemotherapy, could enhance cancer cell death." (PMID 38600086, 2024). "Moreover, this activation of STAT3 enhances the expression of anti-apoptotic proteins, such as Bcl-2, Bcl-XL, and Mcl-1, in cancer cells, thereby increasing resistance to cell death." (PMID 38510850, 2024). "Therefore, blocking the STAT3-Mcl-1 pathway in cancer has been demonstrated to reduce Mcl-1 levels, which in turn promotes programmed cell death in cancer cells." (PMID 39411073, 2024). "Considering the effect of PIAS3 on STAT3, the downregulation of PIAS3 expression may play a critical role in augmenting STAT3 signaling in kidney diseases and cancer development." (PMID 39335615, 2024). "Previous studies suggested that STAT3 activation play a crucial role in the cancer invasion and metastasis by modulating the MMPs expression.Our findings revealed that the expression level of MMP2 and MMP9 was remarkably reduced in MCF-7 cells treated with NAR and DOX." (PMID 38310190, 2024). "In addition, the monoclonal anti-IL-6R antibody tocilizumab increases apoptosis in cancer cells through the IL-6/Jak1/STAT3 axis, promoting tumorigenesis, invasion and antiapoptotic proteins expression in gastric cancer." (PMID 39075612, 2024). "The regulation and inhibition of the IL-6/JAK2/STAT3 pathway is conducive to cancer prevention and treatment as well as improved prognosis and, therefore, represents an important target for designing anti-cancer drugs." (PMID 38715108, 2024). "Over the last decade, different strategies, including small molecules either isolated from natural sources or synthetically produced, anti-sense oligonucleotides, and gene therapy, have been utilized to downregulate STAT3 signaling and thereby inhibit cancer cell proliferation and invasion." (PMID 38256080, 2024). "Studies have shown that STAT3 is overactive in many cancers." (PMID 39056720, 2024). "At the same time, the proposed loop might also provide reference significance for the study of STAT3 and other gene regulatory mechanisms, and provide valuable treatment strategies for cancer." (PMID 38172648, 2024). "These natural products have complex structures due to which they work against cancer through different molecular pathways, STAT3, NF-kB, PI3K/AKT/mTOR, cell cycle arrest, mitochondrial dependent pathway, extrinsic apoptosis pathway, autophagy, mitophagy and ferroptosis." (PMID 38633616, 2024). "Constitutive activity of STAT3 is frequently observed in cancer cells." (PMID 38320998, 2024). "Importantly, we showed that BZA is the first drug to concurrently inhibit both IL-6 and IL-11 signalling and suppress STAT3 activation in cancer cells." (PMID 38600086, 2024). "Constitutive activation of STAT3 has been reported in many cancer types." (PMID 38760429, 2024). "STAT3, an oncogenic transcription factor, is a promising target in cancer therapy." (PMID 39356934, 2024). "Furthermore, signal transducer and activator of transcription 3 (STAT3) signaling is critical in regulating the cell cycle and apoptosis in cancer." (PMID 39590337, 2024). "Interestingly, CD163 is a novel target gene of STAT3 and has been proposed as a therapeutic target in cancer." (PMID 38592450, 2024).
cancer (continued). "STAT3 can either act as a pro-oxidant agent by promoting ROS levels that contribute to cancer progression or as an antioxidant agent by upregulating the antioxidant defensive mechanism, which may protect cells from oxidative stress." (PMID 38397805, 2024). "Cancers that have low IL-6R/STAT3 expression and delayed SOCS3 feedback may alternate metabolic activity in a manner similar to MIA PaCa-2." (PMID 38141171, 2024). "In addition, the critical role of STAT3 as a mediator of the oncogenic effects of EGFR has been demonstrated in several cancers." (PMID 38164181, 2024). "Moreover, PN suppressed the IL-6-induced migration of cancer cells and specifically halted the development of tumors expressing a constitutively active STAT3." (PMID 38397437, 2024). "It has been shown that co-culture of THP1-derived macrophages with ovarian CSCs could promote M2-TAM polarization, and this increased stemness of the cancer cells through IL8 mediated STAT3 signaling." (PMID 39287565, 2024). "NF-κB and STAT3 are crucial transcription factors linking cancer and inflammation." (PMID 39314630, 2024). "Furthermore, its inhibition of STAT3 acetylation impedes the nuclear localization and DNA binding of STAT3, further reducing its transcriptional activity and contributing to its anti-cancer effects." (PMID 39066940, 2024). "Contrarily, it was shown that miR-98-5p is downregulated in ovarian cancer tissues, and its mitigative effects on cancer are hampered by overexpressed lncRNA DSCR8, which is known to promote cancer progression through a highlighted lncRNA DSCR8/miR-98-5p/STAT3/HIF-1α axis." (PMID 38872210, 2024). "Therefore, DH_31 should be considered as a lead compound for the development of STAT3-targeted cancer drugs." (PMID 39195486, 2024). "Notably, the components in the newly identified AKT/mTOR/STAT3/ID1 axis play pivotal roles in cancer metastasis." (PMID 38183094, 2024). "In the context of cancer cell metabolism, STAT3 exerts regulatory control over numerous processes, including aerobic glycolysis 37, oxidative phosphorylation 38, generation of reactive oxygen species (ROS) 39, mitochondrial energy production, and modulation of mitochondrial membrane integrity." (PMID 38495496, 2024). "Stat3 and Akt signaling pathway play a key role in the progression of various cancers." (PMID 38630320, 2024). "IL-6 from CAFs induces EMT through STAT3 in various cancers." (PMID 39201656, 2024). "STAT3 is one of the most commonly activated transcription factors involved in the expression of various target genes promoting tumorigenesis, and therefore is traditionally considered as a promising target for cancer therapy." (PMID 39305962, 2024). "Moreover, the past literature has confirmed that STAT3 plays an important role in the development of various cancers." (PMID 39339184, 2024). "Thus, while nucleic acid therapeutics show promise in targeting STAT3 in cancer, clinical inhibition of STAT3 in GBM is still dependent on the development of effective pharmacological agents which can cross the BBB." (PMID 38615034, 2024). "STAT3 has been a long-standing target for developing cancer therapy, including GI cancers." (PMID 38326371, 2024). "Besides, it was shown that CuI inhibits STAT3 but induces STAT1 through disturbing actin filaments in cancer cell lines." (PMID 38370084, 2024). "Its activation of JAK/STAT3 is the predominant pathway driven by multiple cancer types." (PMID 38103126, 2024). "STAT3 and p-STAT3 protein levels were higher in cancer tissue compared to adjacent tissues." (PMID 39596137, 2024). "Developing a STAT3 inhibitor that simultaneously inhibitsSTAT3 Tyr705 and Ser727 phosphorylation would achieve an adequateinhibition of STAT3, and may achieve a highly potent therapeutic benefitfor cancer treatment." (PMID 38559310, 2024). "Here, we used genetic analyses to identify STAT3 as a relevant dependency in KRAS-driven cancer." (PMID 38573819, 2024).
cancer (continued). "STAT3 has been recently shown to play crucial roles in Texterm cell development in cancer." (PMID 38582965, 2024). "STAT3, a major transcription factor that has crucial functions in cell viability, survival, inflammation, immunity, and the growth, invasion and metastatic potential of many malignances, is abnormally activated in various cancer types." (PMID 38555280, 2024). "Drugs targeting STAT3 activity are being explored as potential cancer treatments." (PMID 38892287, 2024). "Stat3 is involved in the regulation of cell growth, differentiation, apoptosis and other physiological pathways and has become a major target in cancer." (PMID 39173044, 2024). "Additionally, the role of a signal transducer and activator of transcription 3 (STAT3) in cancer biology is pivotal, as it regulates the genes involved in cell growth and apoptosis." (PMID 39519023, 2024). "In this study, STAT3 inhibition by curcumin analog WZ26 showed that it could inhibit cancer cell growth and dreadfully induce ROS levels, leading to regulated mitochondrial apoptosis." (PMID 38397805, 2024). "While EML4-ALK has a driving role in activating downstream signalling cascades such as RAS/MAPK, PI3K/AKT and JAK/STAT3 in EML4-ALK-rearranged cancers, other proteins also feedback into those signalling pathways and might contribute to disease progression." (PMID 39695132, 2024). "Moreover, it is found that C-MYC/AMBRA1/STAT3 axis regulates cancer stemness and invasion potential in MB." (PMID 38561775, 2024). "Notably, miR-21-5p directly targets CCR7, suppressing downstream STAT3 and NF-κB signaling—crucial players in cancer development." (PMID 38542153, 2024). "Therefore, the regulatory pathway of SLC7A11 by the ERO1α/IL-6/STAT3 axis presents in human cancer cells with hyperactivated mTORC1 signaling." (PMID 38610018, 2024). "STAT3 is a transcription factor that is overactivated in most human cancers." (PMID 38172648, 2024). "The STAT3 pathway, a crucial regulator of various cellular processes, including proliferation, survival, and differentiation, is often aberrantly activated in many cancers, including TNBC." (PMID 39770571, 2024). "The mechanism may be that MDSC produces IL-10, which in turn promotes cancer initiation by regulating the STAT3-DNMT3b-IRF8 axis." (PMID 38319729, 2024). "Crosstalk between the CXCL12/CXCR4/ACKR3 axis and the STAT3 signaling pathway has been hypothesized on the basis of findings that both the CXCL12/CXCR4/ACKR3 axis and STAT3 signaling pathway are involved in the progression of several cancers." (PMID 38920657, 2024). "In the direct co-culture supernatant of SKOV3- and THP-1-derived macrophages, IL-8 levels are significantly elevated, leading to macrophage polarization to the M2 phenotype and the induction of stem cell-like characteristics in cancer cells via STAT3 phosphorylation." (PMID 39408927, 2024). "Phosphorylation of STAT3 is associated with increased PD-L1 expression on Treg cells and Indoleamine 2,3-dioxygenase 1(IDO1) on myeloid-derived suppressor cells, frequently observed in dedifferentiated cancer cells and infiltrating lymphocytes." (PMID 38646539, 2024). "Moreover, the STAT3 signaling pathway has the ability to influence apoptosis and autophagy, leading to the destruction of cancer cells." (PMID 38185661, 2024). "Additionally, STAT3-induced autophagy provides a survival advantage to cancer cells under stress conditions, contributing to chemoresistance." (PMID 38892394, 2024). "This review focuses on the up-to-date knowledge of STAT3 signaling in cancer." (PMID 38245798, 2024).
cancer (continued). "It has been reported that natural compounds could affect JAK/STAT3 signaling, leading to enhanced apoptosis and reduced cell proliferation in cancer cells." (PMID 38706884, 2024). "Besides STAT1 and STAT2, other components of the JAK/STAT pathway have been studied in the pathogenesis of cancer, including STAT3." (PMID 39405604, 2024). "Taken together, RACGAP1 may promote STAT3 phosphorylation, nuclear translocation and the expression of STAT3 downstream molecules, such as survivin, to lead to the development of cancers." (PMID 39858398, 2024). "The STAT3 signaling pathway is activated in different cancers, including GC." (PMID 38481347, 2024). "Furthermore, cryptotanshinone significantly inhibited cancer cell proliferation, promoting cell death by reducing STAT3 phosphorylation at Tyr705 and impeding nuclear translocation." (PMID 38397437, 2024). "Finally, we highlight approaches to STAT3 inhibition and novel agents in preclinical and clinical studies targeting STAT3 as a therapeutic strategy for cancer." (PMID 38339245, 2024). "Constitutive or inappropriate activation of STAT3 has been reported in many types of cancers." (PMID 38611065, 2024). "Using a specific inhibitor to target STAT3 could prove to be a valuable strategy in cancer treatment, potentially yielding widespread clinical benefits." (PMID 39305962, 2024). "UANFs could inhibit ERK and STAT3 at the same time, and it is conjectured that UANFs have potential anti-cancer effects." (PMID 39339184, 2024). "While, the inhibitors of JAKs are successfully used in the treatment of cancer and immune-mediated diseases, suggesting that indirect inhibition of STAT3 might be a more promising approach." (PMID 39305962, 2024). "EZH2 may bind to and methylate STAT3, which leads to enhanced STAT3 activity by increased tyrosine STAT3 phosphorylation, suggesting its key role in cancer." (PMID 39204206, 2024). "Src is a tyrosine kinase upstream of STAT3 and is frequently overactivated in different cancers." (PMID 39335615, 2024). "In terms of restraining cSCC, all-trans-retinoic acid (ATRA) represses the overexpressed in some aggressive cancers’ activator protein-1 and diminishes activation of STAT3 in keratinocytes, whereas STAT3 encourages keratinocyte proliferation, which potentially leads to its later malignancy." (PMID 38338469, 2024). "Besides, small-molecule inhibitors targeting downstream elements of the IL-6 signaling pathway, such as JAK and STAT3, show promise in cancer treatment as well." (PMID 39034318, 2024). "STAT3 regulates several pathways critical for cancer metastasis, including cell proliferation, invasion and angiogenesis; thus, Hsp110 may influence apoptosis and cancer development." (PMID 38672583, 2024). "Therefore, understanding the regulatory relationship between STAT3 and ncRNAs and targeting STAT3 or ncRNAs is expected to provide valuable new strategies for cancer disease treatment and drug development." (PMID 38172648, 2024). "The abnormally activated PIK3R3/STAT3 signaling pathway is critical for many cancers." (PMID 39307915, 2024). "IL-25 can also induce JAK/STAT3 signaling pathway to promote self-renewal of cancer cells." (PMID 38818476, 2024). "Interleukin-6/STAT3 are key contributors to cancer growth and progression." (PMID 38519574, 2024). "In addition, Klf4 has been shown to be a downstream target of STAT328, and STAT3 plays a key role in regulating properties and functions of cancer stem cells." (PMID 38509141, 2024). "Understanding the relationship between the CXCL12/CXCR4/ACKR3 axis and the STAT3 pathway could lead to new therapeutic targets for innovative cancer treatments." (PMID 38920657, 2024). "It was also found that TAMs could promote cancer cell chemoresistance by activating STAT3 signaling through secretion of IL-6 and TNF-α." (PMID 39394189, 2024).
cancer (continued). "STAT3 shares a similar relationship with cancer as NF-kB, being stimulated by similar cancer-related pro-inflammatory signals and impacting a number of overlapping cancer hallmarks including proliferation, migration and cancer immunity." (PMID 38195591, 2024). "This underscores the significance of the lncRNA BCAR4/miR-665/STAT3 axis in cancer cell regulation." (PMID 38185635, 2024). "Furthermore, the association between the p63 protein and signal transducer and activator of transcription 3 (STAT3) is emphasized, positing significant roles in preserving cancer stem cells and the carcinogenesis of diverse cellular lineages." (PMID 39734355, 2024). "In this part, we mainly discuss how STAT3 mediates cancer hallmarks activities." (PMID 38245798, 2024). "The evaluation examined how BRB affects survivin expression and STAT3 signaling cascade activity, which could be responsible for cancer’s resistance to 5-FU treatment." (PMID 39125943, 2024). "C3 can also activate the JAK2/STAT3 signalling pathway, that is hypothesized to lead to poorer cancer outcomes." (PMID 38902713, 2024). "At the same time, IL-17A secreted by cancer-associated neutrophils and cancer-associated fibroblasts (CAF) induces the expression of human antigen R (HuR) by activating the JAK2/STAT3 signaling pathway, which recognizes the mRNA encoding Snail and induces its translation." (PMID 39906741, 2024). "Therefore, our results suggest that PRMT1 promotes the proliferation of GSCs by activating STAT3 to upregulate the expression of cancer stemness regulators." (PMID 38474197, 2024). "Aberrant regulation of STAT3 phosphorylation induces the expression of a subset of IL-6-dependent genes that would contribute importantly to diseases, involving altered regulation of immunity or cell proliferation and cancer." (PMID 38533493, 2024). "Thus, STAT3 is a promising drug target for cancer treatment.However, despite over 20 years of effort, the development of STAT3inhibitors has proven to be particularly challenging." (PMID 38559310, 2024). "Moreover, COPS5 is co-expressed with STAT3 in cancers, and MYC mediates this co-regulation associated with poor prognosis." (PMID 38974382, 2024). "Our findings suggest that asymmetrically modified STAT3 homodimers could be a new level of STAT3 regulation and, therefore, a potential target for cancer therapy." (PMID 38150153, 2024). "In addition, the administration of obeticholic acid as an FXR agonist is able to downregulate STAT3, limiting cancer promotion." (PMID 39200261, 2024). "In vitro, STAT3 activation and IL-6 mRNA levels varied greatly among different cancer cell lines." (PMID 38274367, 2024). "Furthermore, the observed reduction in NCI-H2087 cell survival after treatment with NGP-56 highlights the potential of this compound as a cytocidal agent for cancer cells that rely heavily on STAT3 signaling." (PMID 38773495, 2024). "Additionally, we have found that the deletion of USP21 reduced STAT3 activation and STAT3-dependent gene and protein expression in cancer cells." (PMID 39305962, 2024). "Additionally, in primary breast cancer cells, high doses of metformin attenuated cancer progression via suppression of the STAT3 and NF-kB pathways." (PMID 38610965, 2024). "Furthermore, p65 inhibition led to cancer stem cell enrichment in hormone receptor-positive/HER2-negative breast cancer cells, and this effect was mimicked by a STAT3 mutant deficient in the activation of p65 transcriptional activity." (PMID 39201306, 2024). "Therefore, it would be meaningful to further explore the impact of lncRNAs regulating STAT3 expression on cancer recurrence in the future." (PMID 38172648, 2024). "Furthermore, flavonoids influence cancer through a variety of mechanisms in different cancer cells, including oxidative stress, Ras, and STAT3.PEC is a flavonoid mainly found in Cirsium isolates." (PMID 38361124, 2024).